KRAS (KRas proto-oncogene, GTPase)
Diseases named in the same sentence as KRAS in open-access papers (continued):
Sharing a sentence is not in itself a finding about the gene and the disease.
tumor (continued). "Complementing the ICD effect, irinotecan also produces a cell stress response, resulting in PD-L1 expression; this allowed us to demonstrate synergistic boosting of the irinotecan-induced ICD response by anti-PD1 monoclonal antibodies in an orthotopic KRAS tumor model." (PMID 37892935, 2023). "Furthermore, tertiary lymphoid structures (TLS), which target endogenously retroviruses and are protective in vivo, are predictive for response to immunotherapy as demonstrated by a stimulation of anti-tumor B cell responses upon KRAS inhibition." (PMID 37347257, 2023). "As such, blockade of targets such as SHP2 may have particular efficacy with an oncogenic overexpression of WT KRAS protein relative to a tumor with a mutant KRAS protein whose cycling between active and inactive forms is dysregulated." (PMID 36752207, 2023). "The peptides loaded in pHLA tetramers include KRAS-G12wt-9, KRAS-G12V-9 and a subset of KRAS codon 12 and 13 mutant peptides (KRAS-G12C-9, KRAS-G12D-9, KRAS-G12A-9, KRAS-G12S-9, KRAS-G12R-9, or KRAS-G13D-9) frequently observed in tumor specimens." (PMID 37828002, 2023). "This, coupled with the demonstration that treatment of mice bearing mutant KRAS pancreatic PDXs with KRB-456 inhibits P-MEK and P-AKT and induces apoptosis at doses that are tolerable, suggests that KRB-456 inhibits tumor growth at least in part by inhibiting KRAS oncogenic signaling." (PMID 38051103, 2023). "In contrast, by modulating MAPK, mTOR, and JAK/STAT signaling pathways, NLRP1, which is inversely correlated with KRAS, may serve as a tumor suppressor for PDAC." (PMID 37893166, 2023). "The identification of CD4+ TCR specific for KRAS mutations provides the foundation for applying the CD4+ T-cell immunity to the adoptive transfer therapy and deepens the mechanism of CD4+ T cells in human anti-tumor immunity." (PMID 37287989, 2023). "In conclusion, our work uncovers the phospholipid transporter PITPNC1 as a KRAS effector that controls central transcriptional and signalling nodes (i.e. MYC and mTOR) and unveils novel therapeutic strategies for KRAS-driven tumours in the context of a PITPNC1-regulated transcriptional network." (PMID 37210549, 2023). "The obtained data were highly concordant with the results of the visual inspection of the slides, thus suggesting that KRAS/BRAF mutations are not mosaic but present in all tumor cells." (PMID 37686416, 2023). "NDAT also reduced PDL1 levels and tumor growth in HCT116 (KRAS mutant) xenograft mouse models." (PMID 37686465, 2023). "THZ1 administration at both 5 and 10 mg/kg also significantly inhibited the growth of xenograft tumours originating from SW1990 cells with KRAS‐G12D mutation, but no significant discrepancy in the inhibitory effects was noted between the two dose groups." (PMID 38037549, 2023). "However, some studies have reported that KRAS G12V mutations upregulate the expression of CXCR4 and proinflammatory genes in the tumor microenvironment, leading to immune suppression and promoting tumor growth and metastases." (PMID 37415118, 2023). "Elimination of SOS1 specifically induces a decrease in the survival rate of tumor cells carrying a KRAS mutation, while exhibiting no significant impact on those with wild-type KRAS." (PMID 37662925, 2023). "KRAS is a proto-oncogene involving several tumour-related molecular pathways." (PMID 38087207, 2023).
tumor (continued). "Tumor-promoting inflammation is a new concept of immune modality intervention, as it was demonstrated that inflammation has a fundamental role in tumorigenesis and progression in KRAS-mutant NSCLC." (PMID 36899885, 2023). "Investigations have examined GAPDH’s interaction with mutated KRAS and BRAF, suggesting that GAPDH suppression via vitamin C may disrupt tumor growth." (PMID 38134011, 2023). "In immunocompetent male mice and humanized male mice models, SLC25A22 knockout inhibits KRAS-mutant CRC tumor growth with reduced myeloid derived suppressor cells (MDSC) but increased CD8+ T-cells, implying the reversion of mutant KRAS-driven immunosuppression." (PMID 37542037, 2023). "Specifically, the overactivation of KRAS signaling could enhance the excretion of IL-6 resulting in tumor initiation and progression." (PMID 38097680, 2023). "In addition, KRAS G12D mutations and C-Ros oncogene 1 (ROS1) rearrangement were likely to be present in one tumor at the same time." (PMID 37284902, 2023). "Histologically, SMARCA4-DTS is a poorly differentiated tumor with rhabdoid or epithelioid features that can be distinguished from other soft tissue, and thoracic sarcomas by a higher tumor mutation burden (TMB) and the presence of smoking signatures, including KRAS, STK11, and KEAP1 mutations." (PMID 37378131, 2023). "Frequently, mutations in the KRAS gene occur concomitantly with mutations in the GNAS gene in the RAP1 signaling pathway, which involves numerous biological processes, including invasiveness, adhesion, cell migration and polarization, and tumor metastasis." (PMID 37509254, 2023). "Vice versa, FSP1 silencing in KRAS-mutated tumors delayed tumor onset albeit not to the levels of KRAS WT tumors." (PMID 36443441, 2023). "However, despite the comprehensive nature of WGS, only a fraction of cases harboured currently targetable genomic alterations, including small numbers of cases with tumour mutation burden (TMB) > 10 per MB and cases with KRAS and PIK3CA mutations." (PMID 37894318, 2023). "We hypothesize that treatment of ex vivo cultured tumor with anti-KRAS antibody can reduce the membrane localization of KRAS by aggregating KRAS in the cytoplasm." (PMID 37051535, 2023). "Validated through a panel of KRAS-dependent and -independent cell lines in vitro and in vivo, the combination of these respective drugs with Adagrasib exhibited significant dose-dependent tumor regression compared to single agents." (PMID 37190303, 2023). "Cohort stratification into dMMR and pMMR subgroups revealed tumor‐infiltrating cytotoxic CD8+ T‐cell reduction could still be seen in KRAS mutant CRC." (PMID 36599679, 2023). "Moreover, KRAS mutation is associated with decreased CD8 T infiltration and HLA expression in CRC, and, consequently, KRAS mutant tumor cells have a lower chance of being recognized by T cells." (PMID 37563240, 2023). "It was found that the anti-tumour effect of KRAS-siRNA was responsible for lowering the IC50 value." (PMID 36635659, 2023). "KRAS knockdown using Western blot on the collected tumor tissues was observed." (PMID 37872156, 2023).
tumor (continued). "According to the Canadian Consensus Practice Guidelines on tumour biomarker testing for mCRC, the minimum biomarker testing required across all Canadian jurisdictions for mCRC patients requires testing for KRAS/NRAS, BRAF, and MMR/MSI prior to the initiation of 1L therapy." (PMID 37754511, 2023). "Common genes used for CRC DNA mutation detection include BRAF and KRAS, but these tumor markers are not sensitive or specific enough to show CRC." (PMID 36968824, 2023). "Moreover, interestingly, HA‐decorated CP/Ad‐SS‐GD/RNP nanocomplexes (HA/CP/Ad‐SS‐GD/RNP) targeting the KRAS gene were evaluated in an SW480 tumor‐bearing nude mouse model." (PMID 37166046, 2023). "The combination of RAF265 and BEZ 235 (a PI3K inhibitor) significantly inhibited the growth of xenograft tumors with KRAS and RET mutations, suggesting that blocking the ERK and PI3K signaling pathways can effectively inhibit tumor progression in differentiated and medullary thyroid cancer." (PMID 38111008, 2023). "It is noteworthy that KRASG12D protein was clearly evident in the fractions of one patient from each group, suggesting that the isolated EVs specific to PDAC tumour cells, as > 80% of PDAC patients contain mutated KRAS and of which 28% patients carry KRAS point mutation (G>A)." (PMID 36737824, 2023). "Genetic sequence and pathological analysis revealed that these two tumor samples lacked mutations in the KRAS gene and exhibited pathological features of adenocarcinoma, similar to the TPMCa and TPMR1 mouse tumor models." (PMID 37340596, 2023). "In tumor tissues, seven gene amplification mutations included CDK4 (Mutation abundance, MA:1.57), AKT2 (MA:1.65), CCND2 (MA:1.63), MDM2 (MA:1.57), NTRK1 (MA:2.38), AXL (MA:1.65), and KRAS (MA:1.63), as well as the AFF3 gene missense (c.1781_1787del insC)." (PMID 37089080, 2023). "Strategies targeting either KRAS or uPAR should consider this potential tumor-escape mechanism." (PMID 36900379, 2023). "However, despite this limitation, the cases used in the study contained all the radiomic features that demonstrated usefulness in the classification of patients according to their KRAS status, tumor staging, or EMVI." (PMID 38066782, 2023). "Besides, MRTX-1133 inhibited KRAS-dependent signaling and promoted tumor regression in xenograft models." (PMID 37669923, 2023). "Besides, KRAS mutations contribute to forming immunosuppressive tumor microenvironment (TME) and modifying immune cells, resulting in tumor immune escape, and thus potentially reduce the effectiveness of immunotherapy." (PMID 38097680, 2023). "Similarly, both sotorasib and adagrasib have shown promising clinical activity in KRAS G12C PDAC, although these mutations are rare in this tumor type." (PMID 37581538, 2023). "An animal study was performed in B6/129J mice to determine the impact of the liposomes on the subcutaneous growth of a KRAS transformed murine pancreatic adenocarcinoma (KPC) cell line harvested from a spontaneously developing tumor in a transgenic KrasLSL G12D/+; Trp53LSL R172H/+; Pdx-1-Cre mouse." (PMID 37892935, 2023). "Mutations in KRAS resulted in sustained activation of the protein it encoded, so that even if upstream EGFR overexpression is blocked, downstream events cannot be regulated, and tumor growth and proliferation continue." (PMID 37880688, 2023). "In a similar fashion, RMC-6236 is a non-selective RAS(ON) inhibitor that has demonstrated tumor shrinking across various KRAS genotypes, including G12D, G12V, and G12R mutations." (PMID 37569406, 2023).
tumor (continued). "Previous studies of biomarkers in tumor tissues have shown that the mutation status of genes known to be associated with CRC carcinogenesis (NRAS, KRAS, and BRAF) and defects in the DNA mismatch repair system, exert substantial effects on the treatment decision." (PMID 36394150, 2023). "Since adenocarcinomas—the tumor with the highest prevalence of the KRAS mutation —occur at similar rates in LM (72.7%) and HM (85.7%) groups, we confirmed that KRAS mutations were associated with muscularity rather than tumor histopathology." (PMID 36774484, 2023). "The systemic delivery of pacDNA resulted in potent KRAS downregulation and tumor growth inhibition." (PMID 38069255, 2023). "This exploratory study indicated that KRAS may play a role in tumour invasion and metastases and that KRAS status could be a prognostic factor for such events." (PMID 38087207, 2023). "KRASG12C inhibitors have emerged as promising targeted agents for mut KRAS-driven tumours, albeit the clinical data suggest that combinatorial strategies may be required for more durable antitumour responses." (PMID 37210549, 2023). "Treatments targeting either KRAS or uPAR could induce cellular dormancy and render the tumor more resistant to chemotherapy (such as gemcitabine)." (PMID 36900379, 2023). "Our studies demonstrate that SLC25A21 plays a significant role as a tumor suppressor in KRAS-mutant CRC by antagonizing Gln-dependent anaplerosis to limit GTP availability for KRAS activation, which suggests potential alternative therapeutic strategies for KRAS-mutant CRC." (PMID 37937641, 2023). "KRAS overexpression may be one general mechanism by which tumour cells upregulate the expression of the immune checkpoint regulator CTLA-4, thereby evading immune surveillance." (PMID 36902476, 2023). "Ventura and colleagues proposed that pharmacological inhibition of FASN with TVB-3166 reduces cell proliferation and xenograft tumor growth of KRAS mutated NSCLC, but not CRC cell lines via, at least in part, inhibition of the PI3K–AKT–mTOR pathway." (PMID 36675307, 2023). "To determine whether MYCi361 could be a potential therapeutic agent in combination with vincristine to reduce RMS tumor cell growth in vivo, we tested the two-agent combination in the KRAS(G12D)-induced zebrafish FN RMS model." (PMID 37345125, 2023). "Such enhancers can be targeted by bromodomain and extra-terminal (BET) inhibitors (BETi) or degraders and this review discusses whether integrated SOS1 inhibition and BET targeting of MYC synergizes against mutant KRAS tumor growth." (PMID 38023987, 2023). "Phenotype_A was highly enriched in several cancer‐associated pathways, including KRAS, Hedgehog, TGF‐β, hypoxia, angiogenesis signaling pathways, and epithelial‐mesenchymal transition (EMT), suggesting that phenotype_A is related to tumor invasion and metastasis." (PMID 35635121, 2023). "Therefore, oncogenic KRAS partially promotes its early tumor onset through FSP1-mediated ferroptosis protection." (PMID 36443441, 2023). "Having used Tuba-seq to uncover differences in the baseline ability of KRAS G12C and KRAS G12D to initiate lung tumors and drive their growth, we next analyzed the impact of inactivating each of the 28 putative tumor suppressor genes on the growth of lung tumors driven by these oncogenes." (PMID 37828026, 2023).
tumor (continued). "Such an approach may benefit from the combination of oncogenic KRAS signaling inhibition and immune recognition of tumor cells." (PMID 37581538, 2023). "Moreover, Setd2 quantitatively ranks at the apex of all major tumor suppressors for its ability to suppress KRAS-driven cell proliferation." (PMID 36899051, 2023). "The level of circulating tumour DNA (ctDNA) was measured using KRAS peptide nucleic acid clamp‐PCR." (PMID 37341038, 2023). "The findings implied that imaging histological features correlated with KRAS/NRAS/BRAF mutations, and CT may have contributed to CRC tumour genotypes and further facilitate precise therapy." (PMID 37414827, 2023). "In addition, KRAS G12D mutations and C-Ros oncogene 1 (ROS1) rearrangement were likely to be present in one tumor simultaneously." (PMID 37284902, 2023). "The results showed that the siRNA-containing EVs were able to successfully target downregulation of the KRAS gene in cancer cells, which considerably extended the lifespans of mice, while also effectively suppressing tumor growth and promoting apoptosis in tumor tissues." (PMID 37514088, 2023). "STK11/LKB1 loss directly promotes the formation of non-T-cell-inflamed tumor immune microenvironment in immune competent murine models of KRAS-mutant LUAD." (PMID 37261523, 2023). "Additionally, the 3′UTR of the KRAS gene helps regulate it by disrupting complementary sites, which promotes tumor progression." (PMID 37566020, 2023). "Indeed, the effects of tumor suppressor inactivation on growth across oncogenic KRAS-, BRAF-, and EGFR-driven tumors were uncorrelated (Spearman ρ = 0.41 for BRAF versus G12C, ρ = 0.14 for EGFR versus G12C)." (PMID 37828026, 2023). "In the course of strain characterisation work we found that this strain is able to naturally produce high amounts of rasfonin, a polyketide inducing autophagy, apoptosis, necroptosis in human cell lines and showing anti-tumor activity in KRAS-dependent cancer cells." (PMID 37355668, 2023). "In parallel, lactic acid could enhance the sensitivity to AICD induced by anti‐CD3 or autologous tumor cells in tumor‐specific CTLs from CRC patients with wild‐type KRAS." (PMID 36599679, 2023). "The ability to induce ICD in KRAS mutant tumors could explain the potentiation of anti-tumor immunity in our model system, although further investigation as to whether pitavastatin shares this mechanism is required." (PMID 36803614, 2023). "The JACCRO CC-08 trial may have been an outlier when it comes to tumor shrinkage because only one of 34 patients (3%) qualified for a response when re-challenged with CetIri in KRAS wild-type mCRC patients." (PMID 38201553, 2023). "There were frequent mutations in KIT and KRAS, along with frequent focal deletions affecting chromosome regions 1p36.32, 2q11.1, 4q28.1, 5q15.1, and 6p12.1 in YST, and gains in chromosome 12p in all tumours, except pure immature teratomas." (PMID 37372675, 2023). "In addition to the specific genomic sequence variation, tumor site was explored as a potential linkage with KRAS status." (PMID 38032636, 2023). "Recently, two inhibitors (Sotorasib and Adagrasib) were approved by the US Food and Drug Administration (FDA) for the treatment of previously-treated patients with KRAS G12C-mutated NSCLC and are under clinical testing for many other KRAS G12C-mutated tumor types." (PMID 38201431, 2023).